NOX1 (NADPH oxidase 1)
Description:
NADPH oxidase that catalyzes the generation of superoxide from molecular oxygen utilizing NADPH as an electron donor. [Isoform NOH-1L]: NADPH oxidase that catalyzes the generation of superoxide from molecular oxygen utilizing NADPH as an electron donor.
Synonyms: MOX1; NOH1; NOH-1; GP91-2; NOH-1L
Tractability: Small molecule: a drug acting on it is in phase 2 or 3 trials; a high-quality ligand is known; it belongs to a druggable protein family. Antibody: UniProt places it where antibodies can reach, with high confidence; its Gene Ontology location is reachable by antibodies, with high confidence; UniProt predicts a signal peptide or a membrane-spanning region. PROTAC: ubiquitination databases record sites on it; a small molecule that binds it is known.
Target class: Transmembrane 1-electron transfer carriers; Transporter
Chemical probes: ML-090, ML171
Gene: Protein-coding gene on chromosome X (100,843,324 to 100,874,464, reverse strand). Ensembl gene ENSG00000007952.
Subcellular location: Cell projection, invadopodium membrane; Cell membrane
Pathways (Reactome):
Signal Transduction: RAC1 GTPase cycle; RAC3 GTPase cycle; RHO GTPases Activate NADPH Oxidases
Disease: WNT5:FZD7-mediated leishmania damping
Gene Ontology:
Molecular function: protein binding; small GTPase binding; superoxide-generating NAD(P)H oxidase activity; superoxide-generating NADPH oxidase activity; NAD(P)H oxidase H2O2-forming activity; NADP binding; oxidoreductase activity
Biological process: angiogenesis; cell migration; hydrogen peroxide metabolic process; positive regulation of cell population proliferation; positive regulation of integrin biosynthetic process; positive regulation of vascular endothelial growth factor production; superoxide anion generation; defense response; inflammatory response; NADP+ metabolic process; positive regulation of smooth muscle cell proliferation; regulation of blood pressure; respiratory burst; signal transduction
Cellular component: early endosome; NADPH oxidase complex; plasma membrane; cytoplasm; endosome; membrane
Homologues: Orthologues: chimpanzee NOX1 (99% identical), macaque NOX1 (95% identical), dog NOX1 (88% identical), pig NOX1 (85% identical), rabbit NOX1 (85% identical), guinea pig NOX1 (85% identical), mouse Nox1 (84% identical), rat Nox1 (83% identical), tropical clawed frog nox1 (68% identical). Paralogues in human: CYBB (59% identical), NOX3 (57% identical), NOX4 (36% identical), NOX5 (31% identical), DUOX1 (31% identical), DUOX2 (30% identical).
Diseases named in the same sentence as NOX1 in open-access papers:
NOX1 is named in the same sentence as 233 diseases in open-access papers, as found by Europe PMC text mining. Sharing a sentence is not in itself a finding about the gene and the disease. The quoted sentences say what the papers report.
Hypertension (74 papers, 2012 to 2026). The presence of chronic increased pressure in the systemic arterial system. "Herein, we investigated the contribution of NOX1 in obesity-associated hypertension and evaluated the therapeutic potential of pharmacologically targeting NOX1 using the novel inhibitor GKT771." (PMID 41596118, 2026). "Under pathophysiological conditions NOX1, 2 and 5 are upregulated and linked to oxidative stress in hypertension." (PMID 36829839, 2023). "NADPH oxidase is a major source of vascular ROS generation, and Nox2 and Nox1 have been linked to ED in other metabolic and vascular disturbances such as obesity and hypertension." (PMID 35954150, 2022). "Angiotensin II-induced vascular ROS and hypertension is enhanced in transgenic mice overexpressing NOX1 in smooth muscle cells and is suppressed in NOX1 deficient mice." (PMID 36552639, 2022). "NOX1 has been reported to be associated with a variety of cardiovascular diseases, mainly atherosclerosis, hypertension, and ischemia/reperfusion injury." (PMID 36225554, 2022). "Extensive evidence in experimental models of hypertension indicates up-regulation of vascular NOX1, NOX2, and NOX4 as causes of oxidative stress and cardiovascular dysfunction and remodelling." (PMID 34320175, 2022). "Multiple studies have shown that deficiency or overexpression of NOX1 has revealed its role in the pathogenesis of cardiovascular diseases, including atherosclerosis, restenosis, hypertension, and ischemia/reperfusion injury." (PMID 36225554, 2022). "Several genetic polymorphisms of the p22phox gene have been reported to be associated with hypertension and other cardiovascular diseases that can impact NOX1–4 expression and activation." (PMID 34320175, 2022). "Human vascular smooth muscle cells express NOX1, 2, 4, and 5 in physiological and pathological conditions, and those enzymes play roles in most cardiovascular disorders caused by hypertension, diabetes, inflammation, and arteriosclerosis." (PMID 34440716, 2021). "Recently more evidences demonstrated that NOX1 participates in the pathogenesis of cardiovascular diseases including atherosclerosis and hypertension, which are associated with the dysfunction of endothelia cells or vascular smooth muscle cells." (PMID 32001731, 2020). "The progression of hypertension observed in 3-month-old SHRs, was associated with significant elevation of both Nox1 and Nox4 mRNA level in the aortas." (PMID 33131726, 2020). "Ang II and other prohypertensive factors cause upregulation of vascular Nox1 and Nox2, important in redox-mediated hypertension in various experimental models." (PMID 30334629, 2019). "Among the NOX family, NOX1 is particularly implicated in proliferative vascular diseases such as atherosclerosis and hypertension." (PMID 31336911, 2019). "All of these findings suggest that the production of ROS by Nox1 and Nox2 is associated with hypertension." (PMID 28505091, 2017). "Increased activation of Nox1, Nox2 and Nox5 has been demonstrated in hypertension-associated cardiovascular damage, whereas Nox4 activation has been associated with both beneficial and injurious effects." (PMID 28478264, 2017). "Hypertension is widely known to be associated with high levels of ROS and an increase in Nox1 activity and expression." (PMID 25870854, 2015). "NOX1 is also responsible for O·−2generation and is implicated in many pathological conditions including atherosclerosis, diabetes and hypertension." (PMID 25505418, 2014). "Nox1, Nox2, Nox4, and Nox5 of the Nox family are associated with oxidative stress in hypertension." (PMID 39974735, 2025). "Recent in vivo and in vitro evidence indicates that NOX1-derived ROS may underlie enhanced vasoconstrictions in response to angiotensin II in arterial hypertension and vascular diseases." (PMID 37134122, 2023). "NOX1-generated ROS have been implicated in hypertension, suggesting that inhibition of NOX1 may be a promising therapeutic approach." (PMID 35740948, 2022).
Hypertension (continued). "It is therefore possible that PDI and Nox-1 may be implicated in the pathophysiology of platelet hyperactivation observed in obesity and hypertension." (PMID 33806982, 2021). "Angiotensin II type 1 receptor activation and hypertension are linked to increased expression of Nox1 and Nox4 that could lead to vascular damage during chronic hypertension." (PMID 27774507, 2016). "NOX1 was shown to be involved in angiotensin‐II‐mediated hypertension using NOX1‐deficient mice." (PMID 26887821, 2016). "Interestingly, Nox1 is associated with an increased generation of ROS in Ang II infusion hypertension models." (PMID 25870854, 2015). "By constructing transgenic mice overexpressing NOX1 in vascular smooth muscle cells (TgSMCnox1), releasing excessive ROS from NOX1 could cause vascular endothelial cell dysfunction, leading to vessel wall hypertrophy and hypertension." (PMID 36407440, 2022). "The viral proteins, including Tat, induced hypertension through IL-1α-mediated increases in NADPH oxidase 1 (NOX1) as well as subsequent increased Reactive Oxygen Species (ROS) and impaired vasodilation." (PMID 40852711, 2025). "Reduced expression of NCF1 can limit the impact of ELN haploinsufficiency on hypertension by ameliorating the increase of ROS in the vascular walls through regulation of NOX1 and NOX2 NADPH oxidase complexes." (PMID 41292695, 2025). "Previous studies have shown that NOX1 expression and activity are elevated in kidney tissues of inflammatory disease models like hypertension, ischemia-reperfusion injury, hyperuricaemia, diabetes, and hypercholesterolemia." (PMID 40621077, 2025). "Abnormal expression of Nox1 is responsible for the development of various vascular diseases, such as hypertension, atherosclerosis and aortic dissection." (PMID 39721498, 2025). "Recent work using the Tg26 mouse model of HIV shows CD4+ T cells expressing viral proteins can drive hypertension through IL-1α and NOX1 pathways." (PMID 41333751, 2025). "Several studies have revealed the harmful roles of NOX1/2-mediated oxidative stress in hypertension, including but not limited to the inactivation of NO and the production of peroxynitrite." (PMID 39867658, 2024). "In response to high-fat diets, TLR4 knockout prevents obesity-induced endothelial dysfunction and hypertension by reducing NOX1/4 and ROS content, lowering inflammatory factors, and increasing eNOS activity." (PMID 39867658, 2024). "Under normal conditions, the levels of H2O2 and superoxide anion produced by NOX1 are relatively low, but NOX1 acutely activates under various pathological conditions such as ischemia, hypoxia, hyperglycemia, and hypertension." (PMID 36137346, 2022). "Alterations in ROS production and oxidative stress in hypertension are dependent on activation of vascular NOX1, NOX2, and NOX4, as demonstrated in almost all experimental models." (PMID 34320175, 2022). "Studies have shown that NOX1 promotes the progression of atherosclerotic disease, hypertensive disease, and myocardial remodeling through multiple signaling targets." (PMID 36407440, 2022). "While the molecular studies of NOX1 and NOX2 showed their role in promoting hypertension, NOX4 activity has been linked to a protective function." (PMID 34205998, 2021). "Previous studies indicate the link between oxidative stress via NOX1, NOX2, and NOX4 caused by these substances involved in hypertension." (PMID 34440716, 2021). "Acting through angiotensin type 1 (AT1) receptors, Ang-2 stimulates the expression of NOX1, NOX2 and NOX4 homologues and the cytosolic factor p22phox, all implicated in hypertension and associated vascular dysfunction." (PMID 34205998, 2021). "Nox1 knockout reduces ROS levels in models of angiotensin II-induced hypertension (heart and kidney), diabetes, and atherosclerosis." (PMID 32635630, 2020). "At early stage of hypertension (3-months) the most pronounced differences were observed in Nox1 and Nox4." (PMID 33131726, 2020).
Hypertension (continued). "In the present study, we confirmed the increases in the expression of Nox1, Nox2 and Nox4 during the development of spontaneous hypertension." (PMID 33131726, 2020). "While the contribution of Nox1 and Nox2 homologues to experimental hypertension is well established, the role of Nox4 remains disputed." (PMID 33131726, 2020). "In the current study, we further demonstrated the beneficial role of Nox1/4 inhibitor GKT137831 in hypertensive cardiac hypertrophy in a classical model of essential hypertension." (PMID 32831633, 2020). "Originally, NOX1 was described as an NADPH oxidase that stimulated mitogenesis; however, subsequent studies collectively suggested NOX1 to be a driver of hypertension." (PMID 31788367, 2019). "Experimental models have identified a role for Nox1, Nox2, and Nox4 in various cardiovascular pathologies, including hypertension, atherosclerosis, cardiovascular and renal complications of diabetes, and pulmonary hypertension." (PMID 30334629, 2019). "The role of Nox1 in pathophysiology of renal injury is incompletely understood; however, Nox1 is thought to contribute to angiotensin II (Ang II)-mediated hypertension." (PMID 29503620, 2018). "The participation of NOX1 and NOX2 in hypertension is supported by experimental models that show a significant increase of NOX1 expression in vascular smooth muscle cells (VSMC) in hypertensive models." (PMID 30326648, 2018). "AngII is a potent activator of both Nox1 and Nox2, and an impact of Nox enzymes on AngII-induced hypertension has been documented in many previous studies." (PMID 28298457, 2017). "For instance, genetic ablation of Nox1 or Nox2 was shown to elicit beneficial effects on hypertension and vascular dysfunction in certain pathophysiological settings." (PMID 28433660, 2017). "Inhibition of Nox1 and its regulator Rac1/2 with ML171 and EHT1864 respectively, restored hypercontractility suggesting a functional link between Nox1 upregulation and impaired vascular function in hypertension." (PMID 28478264, 2017). "ROS production in response to angiotensin II is related to hypertension, and experimental evidence suggests that Nox1 ROS production is required for angiotensin II hypertension." (PMID 28505091, 2017). "The involvement of Nox and Rac1/2 in hypertension-associated hypercontractility was assessed by pre-incubating vessels with the Rac1/2 inhibitor, EHT1864 or the Nox1 inhibitor, ML171." (PMID 28478264, 2017). "NOX1 is activated by a diabetic state, where hyperglycemia induces AngII and PDGF production that leads to vascular dysfunction and NOX1-ROS production, hypertension and atherosclerosis." (PMID 28230726, 2017). "Adventitial Nox2 is activated in hypertension models while ROS signaling also promotes vSMC hypertrophy via aquaporin 1 and Nox1." (PMID 29135921, 2017). "A key role for Nox1 in redox signaling in angiotensin II (AngII)-dependent models of hypertension has been demonstrated." (PMID 28478264, 2017). "Altogether our results show that PDI expression increases concomitantly to Nox1 in resistance arteries during hypertension development and that this effect is dependent on Ang II signaling through the AT1 receptor." (PMID 25870854, 2015). "The present data corroborates these studies and provides a potential role for PDI in Nox1 derived ROS generation in hypertension." (PMID 25870854, 2015). "Although Nox enzymes participate in a broad array of cellular functions, the role of Nox1 enzymes in cardiovascular disease has been studied mainly in hypertension." (PMID 25137373, 2014). "Nox1 was suggested to be strongly related to vascular physiopathological changes, such as angiotensin II-induced hypertension and aortic dissection and atherosclerosis development in diabetic apolipoprotein E-deficient mice." (PMID 24669283, 2014). "For example, Nox1, Nox2, and Nox4 are increased in several tissues in rats with spontaneous hypertension or angiotensin II-induced hypertension." (PMID 23985827, 2013).
Hypertension (continued). "Two identical NOX1 KO mice carrying a deletion of exons 3–6 have been published showing a mild hypotensive phenotype and attenuated angiotensin II-induced hypertension." (PMID 22648375, 2012). "In obese db/db mice, NOX1 deletion ameliorated hypertension independent of metabolic improvements such as weight loss or improved glucose handling." (PMID 41596118, 2026). "Hypertension produced an increase in the content of superoxide anions in aortic tissue (p < 0.001) along with increased mRNA levels of the prooxidant enzymes Nox1 (p < 0.01) and Nox4 (p < 0.05)." (PMID 39857381, 2025). "Upon angiotensin II stimulation, NOX1 generates ROS, leading to the activation of mitogen-activated protein kinases (MAPKs) and the upregulation of inflammatory cytokines, which contribute to vascular remodeling, hypertension, and atherosclerosis." (PMID 39456418, 2024). "Consequently, overexpression of NOX1 led to increased oxidative stress, elevated blood pressure and hypertrophic response in Ang II-induced hypertension." (PMID 36829839, 2023). "Dual inhibitors of Nox1/4 increase blood pressure and perivascular macrophage infiltration, exacerbating perivascular inflammation and fibrosis levels in models of spontaneous hypertension." (PMID 36407440, 2022). "NOX1 and NOX4 mediate signaling pathways that promote smooth muscle cell proliferation, differentiation, and migration, causing vascular remodeling and exacerbating the progression of atherosclerosis and hypertension." (PMID 36407440, 2022). "Moreover, platelet Nox-1 levels were increased in individuals presenting high blood pressure and central obesity." (PMID 33806982, 2021). "Indeed, in a population study, platelet PDI levels were found to be upregulated in obesity, while platelet Nox-1 was increased in obesity, central obesity and in individuals with high blood pressure." (PMID 33806982, 2021). "In summary, spontaneous hypertension promotes ageing-associated perivascular inflammation which is exacerbated by Nox4 but not Nox1 pharmacological inhibition." (PMID 33131726, 2020). "Pharmacological targeting of Nox1 could be beneficial for slowing down the progression of hypertension-induced kidney damage." (PMID 32635630, 2020). "Therefore, to the best of our knowledge, this is the first report demonstrating a reduction of albuminuria in Nox1 knockout animals in the setting of angiotensin II-induced hypertension." (PMID 32635630, 2020). "Finally, we investigated the effects of pharmacological inhibition of Nox4 and/or Nox1, on perivascular inflammation and perivascular fibrosis in spontaneous hypertension." (PMID 33131726, 2020). "A corresponding study found that mice deficient in NOX4, but not NOX1, are protected from hypertension." (PMID 31239370, 2019). "In terms of renin-angiotensin-aldosterone system–dependent hypertension, Nox2 inhibition would be anticipated to be beneficial, and combined Nox1/Nox2 inhibitors could be of particular value given the effects of both isoforms to increase BP." (PMID 28298457, 2017). "Indeed, Nox1- and Nox2-derived O2- is thought to inactivate NO and enhance hypertension and vascular dysfunction in angiotensin II-induced stress." (PMID 28433660, 2017). "However, the relationship between aldosterone and Nox1 in the context of vascular remodeling in hypertension is incompletely defined." (PMID 28478264, 2017). "We questioned whether aldosterone and oxidative stress play a role in vascular damage in severe hypertension and investigated the role of Nox1 in this process." (PMID 28478264, 2017). "ROS generation mediated by NOX1 is another pathway involved in AngII induced hypertension." (PMID 26121471, 2015). "Therefore, although, the exact mechanisms regarding PDI-NADPH oxidase interaction remains to be elucidated, the present study is the first to provide evidence for the role of PDI in Nox1 signaling in hypertension." (PMID 25870854, 2015).